KRAS (KRas proto-oncogene, GTPase)
Diseases named in the same sentence as KRAS in open-access papers (continued):
Sharing a sentence is not in itself a finding about the gene and the disease.
cancer (continued). "Targeted therapies are licensed for NSCLC (EGFR, ALK, ROS1 indications) and CRC (KRAS wild-type), but KRAS-mutated cancer remains an area of unmet clinical need." (PMID 33130216, 2021). "The oncogene KRAS (which is alternatively spliced into K-Ras4a and K-Ras4b) is the most frequently mutated gene in cancer, so identifying how modifications regulate its activity is of great interest." (PMID 34368168, 2021). "KRAS codon 12 mutations correspond to nearly 90% of all KRAS mutations in pancreatic, colorectal, and lung human cancers." (PMID 35048058, 2021). "Although KRAS is the most mutated oncogene in human cancer, it has considered to be undruggable because of its structural biology." (PMID 33777798, 2021). "KRAS mutations allow cancer cells to grow in lower glucose concentrations than those required for the growth of normal cells." (PMID 34940086, 2021). "Given the prevalence of the KRAS G12C mutation in diverse malignancies, it seems that this (and related) combination strategies can benefit the treatment outcomes of many cancer patients." (PMID 34151545, 2021). "A previous animal study has suggested that the induction of the signature genes FOXA3 or SPDEF, which are enriched in mucin-producing cancers, along with a KRAS mutation in the lung epithelium, is sufficient to develop mucinous lung tumors in transgenic mice." (PMID 34174841, 2021). "Of these, the Ras pathway is the most significant pathway, Ras oncogenes are the most common oncogenes in human cancer, members of this superfamily of GTPases (KRAS, NRAS, and HRAS), which encode four highly conserved Ras proteins sharing 85% homology." (PMID 34513708, 2021). "One trial assesses the safety and efficacy of ELI-002 immunotherapy, a novel amphiphile therapeutic vaccine targeting KRAS-driven cancers, for patients with KRAS or NRAS mutations (G12D or G12R) in various solid tumor types including GBC (NCT04853017)." (PMID 34771420, 2021). "The RAS oncogenes (KRAS, HRAS, and NRAS) are frequently mutated in human cancers, with KRAS being the most commonly affected." (PMID 34947990, 2021). "This crucial role of KRAS and the changes it causes on a bigger scale, makes it an attractive and necessary target for cancer management." (PMID 34781949, 2021). "MAPK signalling pathway is very critical in KRAS-mutated cancers and many inhibitors were developed to target the components of this pathway." (PMID 34781949, 2021). "In cancer cells, KRAS mutations have been shown to give rise to a dependency on exogenous glutamine for growth and proliferation, similar to that observed in MYC amplification." (PMID 34503295, 2021). "Low sensitivity to EGFR inhibitors was confirmed in these KRAS mutated PDOs, both relative to other anti-cancer agents and relative to RAS wild-type PDOs in the reference dataset." (PMID 34496878, 2021). "Notable within these cancer antigens were the GTPase KRAS and the breast carcinoma associated antigen DF3." (PMID 33968037, 2021). "Previous work has implicated the oncogene KRAS as a regulator of cancer metabolism that orchestrates several metabolic pathways, including ER stress pathway." (PMID 33830081, 2021). "Likely as a consequence of their distinct properties, associations have been uncovered between the specific KRAS mutation status and therapeutic responses and clinical outcomes of cancer patients." (PMID 33753749, 2021). "The researchers also found that blocking the IGF1R, MAPK, and PI3K/AKT/mTOR signaling pathways simultaneously led to the death of cancer cells carrying KRAS mutations." (PMID 34257597, 2021).
cancer (continued). "Inhibitors of the MAPK pathway showed greater sensitivity in KRAS mutated cancers compared to the wild-type ones." (PMID 33777798, 2021). "KRAS mutation is one of the most prevalent genetic drivers of cancer development, yet KRAS mutations are until very recently considered undruggable." (PMID 34151545, 2021). "In contrast, we found that RTK-SOS2-WT RAS signaling, but not allosteric SOS2 activation, is a critical mediator of mutant KRAS-driven transformation by protecting KRAS-mutated cancer cells from anoikis." (PMID 33924994, 2021). "RAS mutations (HRAS, NRAS, and KRAS) are among the most common oncogenes, and around 19% of patients with cancer harbor RAS mutations." (PMID 34301278, 2021). "A total of 129 cancer patients with KRAS G12C mutation who received heavy pretreatment joined the Phase I trial (NCT03600883) which showed the safety and efficiency of Sotorasib." (PMID 34781949, 2021). "CRISPR applications in these three particular cancer types, specifically targeting mutations in KRAS and its related molecules are elaborated below." (PMID 34781949, 2021). "In this cohort, the methylation status had significantly higher sensitivity compared to the KRAS mutation status in identifying the cancer patients." (PMID 34968245, 2021). "Once the KRAS gene mutates, it acquires oncogenic properties that are causally involved in the development of human cancers." (PMID 35004317, 2021). "Multiple KRAS-mutant cancers were recently shown to be vulnerable to the loss of SHOC2 in the context of MEK inhibition, confirming the link between SHOC2 and MAP kinase pathway-driven cancers." (PMID 33554860, 2021). "Another report showed in preclinical models that combining a BRAF dimer inhibitor with an MEK inhibitor induced a dramatic therapeutic effect and overcame acquired resistance among cancers with KRAS, NRAS, NF1, BRAF non-V600E, and BRAF V600E mutations." (PMID 34063682, 2021). "Growing evidence supports that LKB1‐deficient KRAS‐driven lung tumors represent a unique therapeutic challenge, displaying strong cancer plasticity that promotes lineage conversion and drug resistance." (PMID 33439550, 2021). "In this review, we address the current status of CRISPR applications for editing KRAS mutations and for editing mutations of KRAS-related molecules, in these three specific cancer types." (PMID 34781949, 2021). "More importantly, we systematically characterized mutation-selection in other cancer driver genes during CRISPR-Cas9 identifying that KRAS mutants can also be selected for, as demonstrated in large-scale genetic screens and Cas9-expressing cell lines." (PMID 34764240, 2021). "The mutations used for analysis were the KRAS G12D and G13D mutations, which are both important in the initiation, progression and drug resistance of many human cancers, leading to a high mortality rate." (PMID 33562505, 2021). "Metabolic reprogramming was mentioned in the previous sections as a frequent phenomenon in many KRAS-mutated cancers." (PMID 34359657, 2021). "The Kirsten rat sarcoma viral oncogene homolog (KRAS) is mutated in approximately 25% of all human cancers and is known to be a major player promoting and maintaining tumorigenesis through the RAS/MAPK pathway." (PMID 33801965, 2021). "In this study, the combinatorial use of an allosteric Akt inhibitor (MK-2206) and different RTK inhibitors (Lapatinib, OSI-906, jnj38877605) reduced the growth of cancer cells harboring KRAS mutations." (PMID 34946644, 2021). "Mutations in the SMARCA4 gene are found in a variety of cancers and tended to co-occur with KRAS mutations frequently (10%)." (PMID 35070984, 2021).
cancer (continued). "This is despite NRas having a high frequency of mutation in malignant melanoma, a cancer associated with UV light exposure, and is due to the higher prevalence of thymine–thymine sites in the KRas gene." (PMID 34680208, 2021). "KRAS is one of the most frequently mutated oncogenes in cancer, being a potent initiator of tumorigenesis, and a predictive target of response to therapy." (PMID 34926275, 2021). "We reasoned that if biological selection is driving KRAS allele selection in cancer, then distinct functions of each mutant form of KRAS would be reflected in cooperating genetic events." (PMID 33753749, 2021). "Human cancers driven by oncogenic KRAS mutations are common and among the most difficult‐to‐treat tumors." (PMID 34369083, 2021). "KRAS mutations are the most frequent mutations in human cancer, and are found in up to 25% of all human cancers." (PMID 34615547, 2021). "Other molecular alterations evaluated to diagnose PDA include KRAS mutations in CTCs, miRNAs in cancer EVs, and heparan sulfate proteoglycan glypican 1 (GPC1) in extracellular vesicles." (PMID 33593396, 2021). "Metabolic reprogramming is an important hallmark of cancer cells and presents a potential method for targeting KRAS driven malignancies." (PMID 33466360, 2021). "The detection of KRAS gene mutations is an important index for tracking the status of oncogenes, highlighting the development and prognosis of various cancers, and determining the effect of radiotherapy and chemotherapy." (PMID 33796026, 2021). "Here, the authors examine the genetic interactions of the different KRAS mutations across multiple cancer types and discover that KRAS mutations have allele- and tissue-specific mutagenic origins, comutation patterns, and dependency interactions." (PMID 33753749, 2021). "Although the association between the KRAS rs712 polymorphism and cancer risk has been widely studied, the effects of this polymorphism on survival of patients with CRC are still unclear." (PMID 33825830, 2021). "With our evolving knowledge regarding the heterogeneity of the KRAS mutated cancers and multiple subtypes of KRAS mutant forms, the precise selection of the patients for cancer-directed therapy will be necessary to ensure efficacy." (PMID 34944853, 2021). "Since KRAS is essential for cell proliferation, indels were detrimental to the cancer cells that contained the specified KRAS mutation." (PMID 34781949, 2021). "This in turn gives us a wide variety of metabolic phenotypes, as seen in cancer cells burdened with the KRAS mutations." (PMID 34572931, 2021). "Another study showed that oncogenic KRAS can activate cancer stem cell properties in APC-mutated cells (loss-of-function mutations that occur during initiation stages of CRCs)." (PMID 33691728, 2021). "Consistent with our analysis in fibroblasts, SCARNA15 expression was remarkably higher in cancer cells with MYC alterations compared to those harbouring KRAS and BRAF mutations." (PMID 34316713, 2021). "As in the other cancer types, presence of KRAS mutations cause resistance to tyrosine kinase inhibitor therapies leading to decreased overall survival and poor prognosis." (PMID 34781949, 2021). "Sotorasib was investigated in patients with cancers with KRAS-G12C mutation and had a disease response in approximately 30% of patients with non-small cell lung cancer." (PMID 34489865, 2021). "Overall, the Pearson correlations between the observed and predicted KRAS allele frequencies for each cancer ranged from 0.4 to 0.6 (or 0.7–0.9 when restricted to just G12 alleles)." (PMID 33753749, 2021).
cancer (continued). "Mutations of the KRas gene are very common in PAC with a frequency of over 90% reported in cancer cells and are associated with a poor prognosis." (PMID 34680208, 2021). "In support of this, recent reports revealed that metabolic dependencies and changes in expression of metabolic genes are linked to the mutant KRAS oncogenes in cancer cells." (PMID 34003553, 2021). "Understanding the frequency of KRAS G12C and co-occurring mutations is crucial to define strategies for cancer control." (PMID 33632153, 2021). "All these data indicate that the nonkinase activities of STK33 can be responsible for its observed essentiality for the cancer cells harboring KRAS mutations." (PMID 34955846, 2021). "Combining the detection of EGFR and KRAS mutations in ctDNA with the detection of protein biomarkers increased cancer detection sensitivity to 74.7% (65/87)." (PMID 33442424, 2021). "The major genetic event in PDAC is an activating point mutation of the KRAS oncogene (70–95%), being permanently activated, and maintaining cancer proliferation, transformation, invasion, and survival." (PMID 33546421, 2021). "It is plausible, that highly mutated cancer genes, such as KRAS, are functionally associated with processes contributing to the emergence of stemness traits." (PMID 33544116, 2021). "RAS mutations occur in 30% of human malignant neoplasms and KRAS is the most frequent mutated oncogene." (PMID 35048058, 2021). "More specifically, the presence of KRAS mutations alone is considered to be insufficient for malignant transformations unless they function in cooperation with a particular set of other cancer-related genes in vivo." (PMID 33982211, 2021). "In order to determine the cause of KRAS independence, authors analyzed cancer-related and DNA damage pathways." (PMID 34781949, 2021). "CDK1 is considered a synthetic target for KRAS-mutated tumors and has been identified as a prognostic marker in numerous types of cancer." (PMID 34917126, 2021). "KRAS mutant cells were incubated with 3-bromopyruvate (3-BrPA), a promising alkylating metabolic inhibitor of cancer with KRAS mutation." (PMID 34298636, 2021). "It has been described as a hallmark of cancer and plays a critical role y KRAS-mutated CRC, as will be described in later sections." (PMID 34359657, 2021). "Together, our findings suggest that a rational approach for treating cancers with KRAS Q61H mutation should consider the inhibition of targets downstream of KRAS." (PMID 34725361, 2021). "Mutational activation of KRAS promotes the initiation and progression of cancers, especially in the colorectum, pancreas, lung, and blood plasma, with varying prevalence of specific activating missense mutations." (PMID 33753749, 2021). "KRAS mutation, such as KRAS (G13D), is the most frequent cancer driver mutation and an intractable anticancer drug." (PMID 34830205, 2021). "It has also been demonstrated that KRAS mutations are key driver events in the metabolic reprogramming of cancer cells." (PMID 33692690, 2021). "The activation of the EGFR-SHP2 pathway maintains newly synthesized KRAS-G12C protein in an active GTP-binding form, thereby leading to the adaptation of KRAS-G12C–mutated cancer cells to ARS-1620." (PMID 34607583, 2021). "We show using Molecular imprinted Polymers (MIPs) and LC-MS/SRM that we can identify the KRAS mutation in cancer patients plasma as well as carry out epitope discovery for drug target evaluation." (PMID 34854867, 2021). "Two of these hotspots presented cancer stage specificity: HRAS G13 mutations were enriched in TMD in late-stage cancers, while KRAS G12 mutations were depleted in early-stage tumors." (PMID 34307377, 2021).
cancer (continued). "The exception, however, is represented by KRAS-mutated cancers where TRAIL signaling was newly found to mediate migration, invasion, and metastasis." (PMID 33791337, 2021). "In MM, SBS9, associated with mutations introduced by polymerase η repair of activation-induced deaminase (AID) activity, was strongly linked with Q61H, the most common KRAS mutation in that cancer." (PMID 33753749, 2021). "The most dramatically enriched oncogenic signatures in Siglec‐XII expressing cells include a set of genes altered in KRAS‐addicted cancers, and a set of TAZ‐associated genes found to be enriched in high‐grade tumors." (PMID 33615152, 2021). "Clinical data show that most cancer patients bearing KRAS mutations have a higher frequency of metastasis and recurrence of disease following radiotherapy." (PMID 34946644, 2021). "SHP2 promotes RAS-driven MAPK signalling, but it is unclear why cancer cells with distinct KRAS mutations exhibit differential sensitivity to SHP2 inhibition." (PMID 34725361, 2021). "KRAS-associated signaling pathways are persistently activated in many cancers, where they participate in cellular growth and proliferation, differentiation, protein synthesis, glucose metabolism, cell survival, and inflammation." (PMID 33917906, 2021). "This review summarizes the role of KRAS activating mutations in multiple cancer types as well as the key findings for potential strategies inhibiting its oncogenic behavior." (PMID 33801965, 2021). "KRAS is commonly mutated at codon 12 in several cancer types, offering a unique opportunity for the development of neoantigen-targeted immunotherapy." (PMID 34272369, 2021). "Cancer cells with KRAS mutations bypass the Gln deprivation-induced G1 checkpoint and instead are blocked in S phase." (PMID 34147108, 2021). "This relationship between EMT and loss of BIM was also observed in KRAS-mutant lung cancers and other cancer subtypes." (PMID 34071428, 2021). "To investigate allele-specific genetic properties, we conducted statistical tests to identify patterns of comutating genes and genetic dependencies for each KRAS allele in each cancer." (PMID 33753749, 2021). "Strikingly, these profound metabolic dependencies were also linked to the addiction of KRAS-mutated cancer to Cu metabolism." (PMID 34440056, 2021). "V941 is an mRNA-based cancer vaccine formulated with lipid nanoparticles that targets four of the most prevalent KRAS mutations (G12D, G12V, G13D and G12C)." (PMID 35083149, 2021). "The preclinical study showed that when cancer cell lines with KRAS mutations were treated with voruciclib, all cell lines had decrease in viability, and reduced MYC levels were noted." (PMID 34944853, 2021). "The GSEA analysis comparing tumors from control and DIO mice revealed that DIO modulated numerous cancer-associated pathways, including hypoxia, KRAS signaling, and the epithelial-to-mesenchymal transition (EMT), as well as one immune-related gene set." (PMID 34944981, 2021). "Overall, the targeting of the guanine nucleotide-binding site of KRAS provides a developmental strategy for targeting the inhibition of KRAS mutations in cancer patients." (PMID 33917906, 2021). "It has been reported, based on a limited number of cases, that cancer cells that harbor KRAS G13D or K/N-RASQ61X mutations are resistant to SHP2 inhibition." (PMID 34725361, 2021). "This study addresses the genetic complexity of cancer through a comprehensive genetic interaction analysis of oncogenic KRAS alleles in COAD, LUAD, MM, and PAAD." (PMID 33753749, 2021). "For example, KRas, a proto-oncogene that is frequently mutated in a wide range of cancers is a well-known driver of resistance to cancer therapy including radiation." (PMID 34733787, 2021). "We estimate KRAS is mutated in only 11% of all cancers, which is less than PIK3CA (13%) and marginally higher than BRAF (8%)." (PMID 34645806, 2021).